TSPO (translocator protein)
Diseases named in the same sentence as TSPO in open-access papers (continued):
Sharing a sentence is not in itself a finding about the gene and the disease.
glioma (continued). "TSPO is expressed in glioma tissues mostly by tumor cells, GAMMs and endothelial cells 18-20." (PMID 33500706, 2021). "Inducible TSPO levels are dramatically increased in microglia under conditions characterized by neuroinflammation, such as multiple sclerosis and glioma." (PMID 34760884, 2021). "Moreover, the levels of angiogenesis regulators such as HIF-1α, VEGF-A, MMP2, and IL-8 were significantly increased in TSPO knockout gliomas in comparison to wild type." (PMID 33066460, 2020). "Additionally, TSPO appears to play a key role in glioma growth and malignancy by controlling the metabolic balance between oxidative phosphorylation and glycolysis." (PMID 33066460, 2020). "However, direct comparison with areas of microglia infiltration (detected by TSPO imaging and/or histopathology) and cortical electrophysiologic data have yet to be reported in human epileptogenic gliomas." (PMID 33291423, 2020). "Indeed, TSPO is frequently upregulated in gliomas with the highest expression in GBM and the level of TSPO expression correlates with proliferative and apoptotic indices and prognosis." (PMID 33066460, 2020). "Likewise, overexpression of TSPO in C6 rat glioma cells enhanced proliferation as well as the ability to overcome contact-induced cell growth inhibition." (PMID 33066460, 2020). "We used synchronized human A172 glioma cells, which are steroidogenic cells with a functional core molecular clock, to show that pregnenolone levels and translocator protein (TSPO) are controlled by the clock, probably via circadian regulation of mitochondrial fusion/fission." (PMID 33086741, 2020). "This PET tracer showed to be highly specific to TSPO in glioma cell line homogenates." (PMID 32283680, 2020). "In addition, PET tracers targeting neuroinflammatory processes, especially those binding to the translocator protein (TSPO, localized predominantly on the outer mitochondria membrane of activated microglia), can accumulate in both gliomas and epileptic tissue." (PMID 33291423, 2020). "In a TSPO knockout GL261 xenograft glioma model, extensive hemorrhages were observed." (PMID 33066460, 2020). "TSPO was reported to increase in different types of tumors, including brain tumors and gliomas." (PMID 32370072, 2020). "Similarly, TSPO was detected in the nuclei of a human glioma cell line and a glioblastoma tumor biopsy, where the presence of TSPO in the nucleus was correlated with tumor aggressiveness." (PMID 31661894, 2019). "Therefore, an additional study demonstrating strong TSPO expression in patients, such as glioma patients, is needed." (PMID 28337723, 2017). "For instance, TSPO-related proliferation has been evaluated in C6 glioma cells in serum-free medium, as well as in a standard fibroblast cell line, showing that nanomolar concentrations of PK11195 and Ro5-4864 increased the growth rate and [3H]thymidine incorporation." (PMID 27367681, 2016). "For example, TSPO expression is upregulated in glioma tumor cells, compared to normal brain." (PMID 27608010, 2016). "Additionally, TSPO expression in GAMs was significantly higher in gliomas in mice treated with EG00229 relative to wt mice." (PMID 26755653, 2016). "We previously demonstrated that high-affinity TSPO radiotracers may be used to visualize gliomas by PET imaging in rats bearing C6 glioma cell allografts." (PMID 26517124, 2015). "Furthermore, it was demonstrated that TSPO positively correlates with proliferation rate but inversely correlates with spontaneous apoptosis rates in various glioma cell lines." (PMID 25663907, 2015). "Translocator protein (TSPO) is a novel and promising biomarker for glioma PET imaging." (PMID 26517124, 2015). "TTN then stimulates neurosynthesis in C6 glioma cells by acting on TSPO." (PMID 24397957, 2014).
glioma (continued). "Increased binding of ligands selective for TSPO has been observed at sites of central nervous system (CNS) pathology, such as glioma 162, 165, 166, 179, multiple sclerosis 21 as well as Alzheimer's disease (AD) 38, and TSPO ligand binding is now seen as a hallmark for microglial activation in vivo." (PMID 25345894, 2014). "We further demonstrate the background-free detection of syngeneic PBR/TSPO-expressing glioma cells growing in the brains of Tspo−/− animals in vitro and in vivo using the selective PBR/TSPO ligands, [3H]PK11195 and [18F]PBR111, as well as antibody staining against the PBR/TSPO." (PMID 25406832, 2014). "In the context of imaging astrocytes in primary brain tumors, numerous glioma cell lines have been shown to highly express TSPO, and recent studies in rat models of glioma suggest that this approach could be used as a clinical tool to detect brain tumors." (PMID 23596394, 2013). "In this way, several groups have evaluated rat models of neuroinflammation using a TSPO radioligand, the 18F-DPA-714, and they have concluded that it provides accurate quantitative information of the density of TSPO after cerebral ischemia, herpes encephalitis and gliomas." (PMID 23300829, 2012). "Notably, TSPO plays dual roles in promoting and inhibiting gliomas." (PMID 40842566, 2025). "There is a potential that stereotactic biopsies in humans may cause similar TSPO-related reactive effects as the inoculation process in rodents and should be paid attention to, as the application of TSPO PET in glioma patients is an area of continuously increasing interest." (PMID 38255293, 2024). "Hence, the time window to monitor the glioma-inherent TSPO signal might be rather short in the GL261 model." (PMID 38255293, 2024). "Thus, overexpression of TSPO in gliomas is not induced by a loss of TSPO promotor methylation, but TSPO promotor subarea hypermethylation might serve as a mechanism to reduce TSPO expression levels in IDH-mutant compared to IDH-wildtype gliomas." (PMID 37697350, 2023). "However, TSPO transcriptional regulation in gliomas is still poorly understood." (PMID 37697350, 2023). "Glioma-induced neuroinflammation could impact the tumor-specificity of TSPO PET imaging." (PMID 36293329, 2022). "We hypothesized that TSPO PET using 18F-DPA-714 may be a potent biomarker strategy, considering that TSPO PET imaging has been used in several gliomas in preclinical and clinical studies presenting high TSPO expression compared to healthy surrounding brain tissue." (PMID 36293329, 2022). "Finally, in vitro subcellular fractionation experiments and co-localization studies, conducted by means of laser scanning confocal microscopy on C6 rat glioma cells, showed the success of this new nanostructure to target mitochondria thanks to the molecular recognition of TSPO." (PMID 34452175, 2021). "Back-translation into a glioblastoma mouse model served to pinpoint the cellular source of elevated TSPO-PET signals and to profile the gene expression signature of distant neuroinflammation in glioma." (PMID 39150564, 2024). "Intriguingly, TSPO expression anticorrelated with RSL3 AUC, suggesting a key role of mitochondrial ROS in driving response to ferroptosis across multiple glioma models (Dataset EV7)." (PMID 39192032, 2024). "Unterrainer and collaborators investigated the correlation between TSPO PET with [18F]-GE-180 PET and glioma biological characteristics in 58 patients affected by newly diagnosed (n = 33) or recurrent (n = 25) brain tumors." (PMID 37238297, 2023). "DPA-BSTPG, a boron-10 compound targeting TSPO, provided an effective BNCT against the F98 rat glioma model." (PMID 36831378, 2023). "A literature search for studies about TSPO PET in the last 10 years (from 2013 to February 2023) was carried out on PubMed, Scopus, and Web of Science using the following keywords: “PET” AND “Gliomas” AND “TSPO”." (PMID 37238297, 2023).
glioma (continued). "For example, 18F-DPA-714 is a radiotracer targeting the 18 kDa translocator protein (TSPO), comparable to 18F-FET PET for detecting tumors when trialed in a mouse model of infiltrative human glioma." (PMID 36483050, 2022). "Notable among these is the tumor inflammation specific [18F]DPA-714, a ligand of the translocator protein (TSPO), expressed in glioma cells." (PMID 35303961, 2022). "Finally, TSPO might be taken into consideration (i) for developing personalized and targeted therapies and (ii) to identify novel options for immunotherapy for patients with glioma." (PMID 33500706, 2021). "The prototypical radioligand for TSPO is [11C]-(R)-PK11195, which was first used for human brain imaging in 1989 to study glioma and was subsequently applied to a variety of neurological and peripheral pathologies." (PMID 33693967, 2021). "TSPO-PET imaging is increasingly being used in neuro-oncology, especially in glioma patients, and has been shown to be a useful tool for assessing tumor progression at follow-up." (PMID 34572751, 2021). "Given the clinical interest, TSPO positron-emission tomography (PET) imaging has been used in a wide variety of neuroinflammatory conditions, including high-grade gliomas." (PMID 34572751, 2021). "TSPO was expressed predominantly by neoplastic cells, and its ligand, 11C-(R)PK11195, binds more strongly in high-grade gliomas than in low-grade gliomas." (PMID 31737567, 2019). "During the last two decades, the prototypic TSPO radioligand in use has been (11C)-PK11195, with the first human brain studies conducted in patients with Rasmussen’s encephalitis, with glioma, and in healthy controls and MS patients." (PMID 30696113, 2019). "Initial positron emission tomography imaging of a glioma bearing mouse and a healthy baboon support the potential for [18F]-AB5186 use as a radiotracer for non-invasive TSPO imaging in vivo." (PMID 29142713, 2015). "TSPO immunoreactivity was evaluated in tumor microarrays (TMAs) of pilocytic astrocytoma (WHO grade I) and high-grade (WHO grades III and IV) glioma." (PMID 26517124, 2015). "According to several studies, there is a positive correlation between TSPO expression and the grade of malignancy and glioma cell proliferation; however, it has a negative correlation with survival in patients with glioma." (PMID 39355049, 2023). "Conversely, F98 and C6 rat glioma cells may be more likely to benefit not only from BPA-BNCT, but also from TSPO-targeted BNCT." (PMID 36831378, 2023). "In conclusion, our study improves the understanding of TSPO as an imaging marker in gliomas by unveiling IDH-dependent differences in TSPO expression/regulation, regional heterogeneity of the TSPO PET signal and functional implications of TSPO in terms of tumor immune cell interactions." (PMID 37697350, 2023). "Previous studies showed TSPO overexpression in gliomas compared to non-neoplastic brain tissue and suggested positive correlation of TSPO expression and glioma malignancy." (PMID 37697350, 2023). "The higher the TSPO expression, the higher WHO grading of gliomas, and thus there is a negative correlation between TSPO expression and survival and a positive correlation with tumor proliferative potential." (PMID 36831378, 2023). "Blood brain barrier (BBB) penetrance remains an issue for TSPO imaging but is not a limitation for brain tumors in general or for gliomas per se since the brain blood barrier is disrupted in the vast majority of HGGs." (PMID 35303961, 2022). "Nevertheless, the function of TSPO in glioma or its potential molecular mechanism has not been fully detailed." (PMID 36278207, 2022). "TSPO has become more important as a positron emission tomography (PET) imaging target for several diseases, including CNS autoimmune diseases, neurodegeneration and glioma." (PMID 34073557, 2021).
glioma (continued). "We and others showed that [18F]DPA-714 supports the identification of unique TSPO-expressing regions of the TME 20,22 that may represent areas with immunosuppressive myeloid cells 23 and glioma infiltration 24,54." (PMID 33500706, 2021). "Several studies have shown a positive correlation between TSPO expression and grade of malignancy and glioma cell proliferation and a negative correlation with survival in glioma patients." (PMID 34572751, 2021). "Here, we report an animal model that allows high-contrast imaging of wild-type glioma cells by positron emission tomography (PET) using [18 F]PBR111, a selective radioligand for the mitochondrial 18 kDa Translocator Protein (TSPO), in the Tspo−/− mouse strain (C57BL/6-Tspotm1GuMu(GuwiyangWurra))." (PMID 32561881, 2020). "In our study, we showed that StAR and CYP11A1 did not display any significant circadian variations in glioma cells, whereas TSPO levels followed a circadian rhythm in vitro and in vivo (mouse brain lysates)." (PMID 33086741, 2020). "A negative correlation between the CNPase and TSPO levels in HL-60 and glioma C6 cells (unpublished data) was observed." (PMID 32722345, 2020). "In addition, TSPO expression was positively correlated with most immune cell types in both glioblastoma and lower-grade glioma, except for negative correlations observed with type 2 T helper cells and memory B cells." (PMID 38162485, 2023). "The 9L rat glioma cells may benefit from BPA-BNCT, but may benefit less from TSPO-targeted BNCT." (PMID 36831378, 2023). "TSPO imaging and IDH mutational status confer a trend towards higher 18F-GE-180-uptake in IDH-wild-type gliomas in the overall group, albeit that this trend was not confirmed in identical WHO grade gliomas." (PMID 35303961, 2022). "In addition, [18F]-AB5186 6 exhibited the ability to image TSPO in an intracranial glioma bearing mouse and to penetrate the intact BBB in a non-human primate." (PMID 29142713, 2015). "Several groups have also evaluated neuroinflammation models in rats using the TSPO radioligand 18 F-DPA-714, concluding that it provides accurate quantitative information of TSPO density after cerebral ischemia, herpes encephalitis, amyotrophic lateral sclerosis, and gliomas." (PMID 25006546, 2014). "It is already known that BPA is non-uniformly distributed in gliomas when BPA is administered, and furthermore, glioblastoma has proven inter-individual heterogeneity of TSPO and LAT1 expression in neoplastic and parenchymal cells." (PMID 36831378, 2023). "Mean methylation scores in the identified TSPO CpG island subarea were high in IDH-mutant and low or absent in IDH-wildtype gliomas (p < 0.001)." (PMID 37697350, 2023). "Currently, however, imaging of gliomas with PET TSPO ligands is not standardized, and it remains unclear to which degree the TSPO PET signal reflects tumor cells or activated microglia." (PMID 33066460, 2020).
depression (64 papers, 2015 to 2026). "The anterior cingulate cortex is also frequently implicated in studies of depression utilizing positron emission tomography targeting translocator protein, which is interpreted as indicating microglial activation or neuroinflammation." (PMID 39312956, 2025). "Remarkably, the impact of TSPO deficiency on mitochondrial bioenergetics closely resembles parameters of mitochondrial function observed in a human cell model of depression." (PMID 39684592, 2024). "Using a human cell model of depression, our group found mitochondrial function to be altered in a way similar to what we observed in TSPO-deficient cells." (PMID 39684592, 2024). "TSPO has already been linked to anxiety and depression disorders, making it a potential diagnostic and therapeutic target." (PMID 39684592, 2024). "Additional longitudinal imaging-based studies have the potential to offer more robust evidence confirming the utility of TSPO imaging as a prognostic biomarker associated with the development of depression." (PMID 35113011, 2022). "We also undertook an exploratory search for possible associations of TSPO PET results with depression severity, body mass index (BMI), and other factors." (PMID 36226319, 2022). "Depression-associated elevations in TSPO in the prefrontal cortex, insula, and anterior cingulate cortex have been correlated with the severity and duration of depression." (PMID 30687139, 2018). "Indeed, Microglial activation levels (TSPO-VT) were notably linked to persistent severe depression, particularly in the ACC, frontal cortex, and insula of patients without long-term antidepressant." (PMID 38916735, 2024). "Furthermore, TSPO overexpression in the hippocampus attenuated depression-like behaviors associated with increased neurosteroid synthesis." (PMID 36732752, 2023). "In addition, mitochondrial dysfunction is increasingly associated with depression by promoting the translocator protein (TSPO) mediated mitophagy signaling pathway." (PMID 37521479, 2023). "We focused on TSPO PET results in the five brain regions most frequently reported in the eight studies included in our meta-analysis, with a consistent finding of increased TSPO expression in key cortical regions associated with the pathophysiology of depression." (PMID 36226319, 2022). "However, reduced TSPO expression has been observed in patients with co-morbidities of anxiety and depression or bipolar disorder and has been associated with distress and aggression." (PMID 29506545, 2018). "TSPO polymorphism (Rs6971; Ala147Thr) has been also proposed to affect the hypothalamic–pituitary–adrenal axis predisposing carriers to psychiatric disorders, e.g. bipolar disorders, depression, and anxiety, and affects the response of patients to anxiolytic TSPO drug ligands." (PMID 29074640, 2017). "Disruption of the BBB (via enlargement of the choroid plexus) has been observed to overlap with increases in neuroinflammation (indicated by greater translocator protein (TSPO) binding) in people with depression." (PMID 40308263, 2025). "In the pathogenesis of depression, translocator protein (TSPO), as an important regulator of mitophagy, has also received extensive attention." (PMID 40497971, 2025). "Growing evidence indicates brain inflammation in depression in the form of heightened translocator protein (TSPO) expression, and increased IL-6 and TNF-α in the cerebrospinal fluid (CSF)." (PMID 39959848, 2025). "The translocator protein (TSPO) has gained attention as a potential biomarker of neuroinflammation in depression." (PMID 40004109, 2025). "This measure was correlated with brain TSPO expression and peripheral cytokine concentrations in a cohort enriched for heightened peripheral and central immunity comprising 51 individuals with depression and 25 healthy controls." (PMID 39657983, 2025).